CD68 (CD68 molecule)
Diseases named in the same sentence as CD68 in open-access papers (continued):
Sharing a sentence is not in itself a finding about the gene and the disease.
pulmonary fibrosis (13 papers, 2005 to 2025). Chronic progressive interstitial lung disorder characterized by the replacement of the lung tissue by connective tissue, leading to progressive dyspnea, respiratory failure, or right heart failure. "M2‐like macrophage markers (CD163 and CD204) and CD163/CD68 and CD204/CD68 cell ratios are significantly elevated in idiopathic pulmonary fibrosis (IPF) patients, associating with shorter overall survival and time‐to‐acute exacerbation in IPF patients." (PMID 33080104, 2020). "In fibrosing alveolitis, macrophages (CD68+) and eosinophils are key sources of CCL5, with CCL5 correlating with eosinophil numbers in pulmonary fibrosis caused by sulfur mustard gas inhalation, suggesting a potential role of CCL5 in acting on CCR3 and contributing to eosinophilia during fibrosis." (PMID 39768150, 2024). "Besides, we examined the expression of USP25 and macrophages (marked CD68) in fibrotic lungs of idiopathic pulmonary fibrosis (IPF) patients, and immunofluorescence showed that USP25 was highly expressed in fibrotic tissues and co-localized mainly with macrophages." (PMID 39781451, 2025). "Similarly, CCL5 is expressed by alveolar macrophages, macrophages (CD68+), and eosinophils as key sources in fibrosing alveolitis, with a positive correlation between CCL5 levels and eosinophils in pulmonary fibrosis." (PMID 39768150, 2024). "We previously reported that in lung pathology of ILD in patients with microscopic polyangiitis, chemokine C-C motif ligand 2 (CCL2)-producing CD68+/CD163+ macrophages infiltrate the alveoli, and serum CCL2 levels significantly correlate with the progression of lung fibrosis." (PMID 36077067, 2022). "Given the number of CD206 + macrophages, but not CD163+, CD68+, CD86+ or iNOS+ macrophages, was markedly decreased upon microcystin-LR treatment, it was reasonable to assume that microcystin-LR could meliorate pulmonary fibrosis mainly by suppressing CD206+ M2a-like macrophage differentiation." (PMID 32075954, 2020).
type 2 diabetes (13 papers, 2013 to 2025). "Consistent with a proinflammatory state, several key cell surface antigens (Cd4, Cd68, Cd84), immune sensors (Cx3cr1, Clec7a), and macrophage genes (Axl, Slc11a1) were upregulated in hIAPP islets and in type 2 diabetes." (PMID 34554282, 2022). "We previously reported the increased aggregation of epidermal CD207-positive LCs and subepidermal CD68-positive macrophages in hind paw skin of db/db mice, a mouse model of type 2 diabetes, during mechanical allodynia." (PMID 29408929, 2018). "In insulitic donors with type 2 diabetes, the pancreases were characterised according to the presence of CD68 (macrophages), myeloperoxidase (MPO; neutrophils), CD3, CD20 (B cells) and HLA class I hyperstained islets." (PMID 27796420, 2017). "In visceral adipose tissue, MCR1/CD68 ratio was reduced in obese subjects, mainly in those with type 2 diabetes, whereas CD68 gene expression was increased." (PMID 23951013, 2013). "Obese women with type 2 diabetes (T2D) and chronic inflammatory diseases are at higher risk of breast cancer, asT2D with obesity mediates the production of IL6, IL7, and CD68 macrophages, such as proinflammatory cytokines, which exacerbate the invasion of metastatic cancerous cells." (PMID 35401196, 2022). "Inflammation mediated by CD45+ cells, mainly CD68+ macrophages, may also directly affect islet function and survival, arguing for a direct role of these cells in the pathogenesis of type 2 diabetes." (PMID 27796420, 2017). "The shift toward a proinflammatory EAT secretome has also been observed in type 2 diabetes mellitus (T2DM), with a reduction in adiponectin and increase in expression of MCP-1 and CD68+ cells compared with nondiabetic counterparts." (PMID 34890279, 2022).
Erdheim-Chester disease (12 papers, 2018 to 2026). "Alternative histiocytic disorders, including Rosai-Dorfman disease and Erdheim-Chester disease, which are typically CD68 positive, were considered." (PMID 40979825, 2025). "Erdheim-Chester disease (ECD) is a rare multisystemic disease characterized by the infiltration of multiple organs by foamy CD68 + CD1a-histiocytes." (PMID 38669404, 2024). "Erdheim-Chester disease (ECD) is a rare non-Langerhans cell histiocytosis caused by the expression of CD68-positive and CD1a-negative foam tissue cells, which is polar in pediatric patients." (PMID 35494046, 2022). "Pathology of Non-Langerhans histiocytosis such as Erdheim-Chester disease involves characteristic Touton giant cells that are CD68 positive and CD1a negative." (PMID 35418930, 2022). "Diagnosis was suggested by xanthomatous skin lesions and a biopsy was compatible with Erdheim-Chester disease demonstrating xanthogranulomas CD68 positive (clone KP1) and CD1a and S100 negative." (PMID 33602153, 2021). "Erdheim-Chester disease, on the other hand, is positive for CD68 and CD163, may express factor XIIIa, and is negative for langerin and CD1a; S100 may also be expressed." (PMID 40398847, 2025). "Erdheim-Chester disease (ECD) is a rare histiocytic disorder characterized by the infiltration of tissues with foamy, xanthomatous CD68/CD163-positive, CD1a-negative histiocytosis." (PMID 41994452, 2026).
Insulin resistance (12 papers, 2010 to 2022). Increased resistance towards insulin, that is, diminished effectiveness of insulin in reducing blood glucose levels. "The insulin resistance in obese mice was associated with the increased expression of inflammatory markers Cd68, Il-6 and Il-1α; in contrast, most of these genes were down-regulated in CR mice." (PMID 20307313, 2010). "In the present study, we observed relationships between high adiposity, insulin resistance, and the adipose tissue expression of macrophage cell surface receptor CD68." (PMID 21197447, 2010). "In our study, the CD68 inflammatory cells infiltration indicated that smoking might contribute to insulin resistance and hyperglycemia through increasing inflammatory cytokines levels." (PMID 29437243, 2018). "The expression of CD68 was significantly correlated with patients plasma FFA levels and the degree of insulin resistance of the patients." (PMID 25337938, 2014). "Our study extends this observation further and suggests that adipose tissue inflammation reflected by increases in CD68 and TNF-α expressions plays an important role in the whole-body insulin resistance in patients with COPD." (PMID 21197447, 2010). "Irrespective of insulin resistance severity, mRNA levels of collagens correlated reciprocally and with macrophage markers CD68 (Col I: r=0.4, P<0.01; Col III: r=0.47, P<0.01; Col VI: r=0.59, P<0.05) and MCP-1 (Col III: r=0.38, P<0.05; Col VI: r=0.4, P<0.05)." (PMID 26258766, 2015). "However, in livers from 1YO offspring of WSD-fed mothers with insulin resistance, we found an increase in macrophage recruitment and markers of inflammation, including IL1B, CD68, and CD11B in whole-liver tissue, and isolated hepatic macrophages were hyperresponsive to LPS." (PMID 34935645, 2021).
oral squamous cell carcinoma (12 papers, 2016 to 2025). "More recent studies revealed that CAFs release chemokines to recruit MØs to the tumor, and the infiltration of CAFs are associated with the number of CD68+ or CD163+ MØs in patients with oral squamous cell carcinoma." (PMID 37254126, 2023). "In HNSCC, NPC, and RCC, apCAFs show a significant negative correlation with Tregs, similar to findings where CAFs expressing the macrophage classical marker CD68 in oral squamous cell carcinoma is found to inhibit Tregs infiltration." (PMID 38903527, 2024). "Macrophage polarization to M2-type is characterized by CD163 expression in oral squamous cell carcinoma, and the CD163/CD68 ratio can be used as a measure for M2 polarization." (PMID 41511327, 2025). "This study investigated the clinical relevance of TAM infiltration in oral squamous cell carcinoma (OSCC), evaluating CD68 (M1 and M2 macrophage marker) and CD163 expression (M2 macrophage marker) in the tumor nests and surrounding stroma." (PMID 32630659, 2020). "Clinicopathological evaluations of oral squamous cell carcinoma tissue samples revealed that both high grade (0: negative, 1: scanty, 2: focal, 3: abundant) of CAFs and high number of CD68+ macrophages were correlated with the TNM stage." (PMID 34336660, 2021). "In oral squamous cell carcinoma (OSCC) patient samples, metastatic tumors had the highest percentage of CD68+ TAMs, followed by non-metastatic samples and the control." (PMID 41511327, 2025).
schwannoma (12 papers, 2006 to 2024). A benign, usually encapsulated slow growing tumor composed of Schwann cells. "As a result, the existence of a greater number of CD68 histiocytes in a schwannoma can cause angiopoietin-Tie-2 interactions and consecutive extensive vascular proliferation." (PMID 34824953, 2021). "More recently, based on the evidence that monoclonal antibody KP-1, which recognizes the lysosome-associated glycoprotein CD68, reacts positively with schwannomas and granular cell tumours, it is believed that these tumours arise from Schwann's cells." (PMID 16930486, 2006). "GCTs and schwannomas have significantly different expressions of the lysosomal marker CD68, with GCTs staining strongly and diffusely and schwannomas staining weakly in only a small number of cells." (PMID 35323240, 2022). "Schwannoma staining was variable: one case was void of any appreciable staining for CD68 immunoreactivity, while the remaining 9 cases had low to moderate staining." (PMID 35323240, 2022). "The number of cd68-positive cells, tumor size, tumor growth index, and increase in tumor microvessel density have a clear correlation with the vascular density of a schwannoma." (PMID 34824953, 2021). "There has been comparatively less research into the role of TAMs in NF2-related VS, but small histopathological studies have demonstrated Iba1 and CD68-positive macrophage occurrence among human schwannoma samples." (PMID 32642684, 2020). "CD68: CD68 immunoreactivity was restricted to the cytoplasm of both GCTs and schwannomas." (PMID 35323240, 2022). "Ultimately, macrophage occurrence indicated by both CD68 and Iba-1 expression was also found in 28 out of 30 human biopsy samples from sporadic schwannomas, 9 out of 10 NF2-related schwannomas and in 4 out of 4 investigated Schwann cell tumors associated with schwannomatosis." (PMID 27236462, 2016). "The KP-1 monoclonal antibody, which recognises the lysosome-associated glycoprotein CD68, reacts positive with schwannomas and granular cell tumours but not with other neuronal neoplasms." (PMID 20184692, 2009). "In support of these phenotypes, immunohistochemistry for CD68, CD3, and PD1 was greater in immune-enriched compared to neural crest schwannomas." (PMID 38216587, 2024). "This study aims to differentiate an antigen-presenting cell (APC) phenotype from a neural tissue phenotype in GCTs using immunohistochemistry (HLA-DR, CD68, CD163, CD40 and CD11c for APC), and polymerase chain reaction and to compare this expression profile with schwannomas." (PMID 35323240, 2022). "Immunoreactivity to CD68, HLA-DR, CD163, CD40 and CD11c (APC phenotype) and markers of neural crest cell (NCC) origin S100, SOX10, NSE and GAP43 in 23 cases of GCTs and 10 cases of Schwannomas were evaluated." (PMID 35323240, 2022). "With reference to the phenotype, the cellular population showed a clear positivity for Vimentin only, being S100 and CD68 negative, which excluded the schwannoma and the MFH, respectively." (PMID 24266985, 2013). "Although there was strong staining for CD68 in both GCT and schwannomas in previous studies which strengthen the histogenetic relationship between GCT and Schwann cells, we couldnot observe such relation in our cases which expressed weak positive staining in only 35.7% of cases." (PMID 22132340, 2011).
steatosis (12 papers, 2013 to 2024). Increased lipid within the cytoplasm of cells. "Steatosis with obvious lipid accumulation and an increased number of CD68+ cells were evident in HFD+PTU_4w and HFD_8w." (PMID 39409093, 2024). "A fourth study suggests that Gal-3 has multiple roles in NASH, with CD68/Gal-3+ cells decreasing with severity of steatosis and NASH and α-smooth muscle actin/Gal-3+ cells increasing with severity of fibrosis." (PMID 33203036, 2020). "In fact, in the liver, the pan-macrophage marker CD68 was frequently co-expressed with Gal-3 and the number of double-positive cells was reduced in groups with steatosis, hepatocyte ballooning, and NASH." (PMID 31337151, 2019). "Quantitative analysis also revealed that the number of CD68/CD206/Gal-3+ macrophages was significantly reduced in patients with steatosis and exhibited a trend of decrease in NASH." (PMID 31337151, 2019). "Accordingly, we found that the CD68/CD206/Gal-3+ M2 macrophage number was reduced in patients with steatosis and NASH with a high grade of portal inflammation, or ballooning." (PMID 31337151, 2019). "CD68 macrophages expressed Gal-3 but the number CD68/Gal-3 positive cells was significantly reduced in patients diagnosed with steatosis and NASH." (PMID 31337151, 2019). "Accordingly to the trend of CD68 pattern, the number of CD68/Gal-3+ macrophages was also significantly reduced only in patients diagnosed with steatosis and NASH." (PMID 31337151, 2019). "The number of CD68+ macrophages was significantly reduced in patients with steatosis and NASH." (PMID 31337151, 2019). "Moreover, Spearman correlations showed that the number of liver-resident cells that expressed CD68 were inversely correlated with the presence of steatosis (r = −0.54, p < 0.001) and with NAS (r = −0.35, p = 0.05)." (PMID 31337151, 2019). "Furthermore, immunohistochemistry study showed more F4/80-positive and CD68+ cell infiltration in the Hsd17b1333A/A mice, suggesting that the 17β-HSD13 S33A mutation caused steatosis and hepatocyte injury may trigger liver inflammation." (PMID 36323699, 2022). "Morphological analysis revealed that CD68/Gal-3+ macrophages were preferentially observed in the hepatic portal zone of no steatosis group." (PMID 31337151, 2019). "In particular, the number of CD68+, S100A9+, and CD206+ macrophages was correlated with NAS score; moreover, the number of S100A9+ and CD206+ macrophages was correlated with steatosis and hepatocyte ballooning." (PMID 27310371, 2016). "Hepatocyte iron storage, ongoing portal track development, acinar bile ducts, macrovesicular hepatocyte steatosis, hepatocyte apoptotic bodies, lobular atrophy, CK7 scores, and CD68 scores were not significantly different across groups." (PMID 32150543, 2020). "Triple CD68/CD206/Gal-3, which represented the subpopulation of M2 macrophages, were mainly present in patients without NASH, and clearly reduced in patients with steatosis and NASH." (PMID 31337151, 2019).
Cognitive impairment (11 papers, 2016 to 2026). Abnormal cognition is characterized by deficits in thinking, reasoning, or remembering. "However, CD68+ microglia still surpassed the control and were close to that on day 28, suggesting that microglia continued to conduct phagocytosis even during HS, which consisted of a major cause of cognitive impairment in epilepsy." (PMID 37072932, 2023). "Moreover, CD68-positivity rate correlates with AD-associated cognitive impairment." (PMID 31540372, 2019). "Immunotherapy alone or in combination with radiotherapy induces cognitive impairments, increases in CD68+ microglial immunostaining and central cytokine production." (PMID 29930550, 2018). "Our study in particular builds upon these findings by quantifying intensity, morphological and spatial features of microglia, demonstrating a correlation between CD68+ and pTDP‐43+ staining and suggesting a role for extra‐motor microglial activation in cognitive impairment." (PMID 36070099, 2022). "Moreover, the consistent CD68 upregulation is positively correlated with AD pathology and cognitive impairment." (PMID 35806318, 2022). "In addition, chronic cyclophosphamide treatment in athymic nude rats induces microglial activation (increased CD68+ cells) in the hippocampus, as well as cognitive impairments in hippocampal and cortical-dependent tasks." (PMID 29930550, 2018). "Animals receiving the PLX5622 diet exhibited no radiation-induced cognitive deficits, and exhibited near complete loss of IBA-1 and CD68 positive microglia in the mPFC and hippocampus." (PMID 27516055, 2016). "PLX5622-treated mice exhibited no ADR-related cognitive deficits and near complete depletion of IBA-1 and CD68+ microglia in the brain." (PMID 31753024, 2019).
granular cell tumor (11 papers, 2011 to 2026). An unusual benign or malignant neoplasm characterized by the presence of neoplastic large polygonal cells with granular, eosinophilic cytoplasm which contains abundant lysosomes. "Final histopathological and immunohistochemical evaluation demonstrated polygonal cells with abundant eosinophilic granular cytoplasm and positivity for S100 and CD68, consistent with a granular cell tumor." (PMID 42186624, 2026). "Immunohistochemically, the tumor cells are positive for S100 and CD68 consistent with classic granular cell tumor." (PMID 36827062, 2023). "Immunohistochemically, the tumor cells were positive for S100 and CD68, which is consistent with classic granular cell tumors." (PMID 36827062, 2023). "Immunohistochemistry findings confirmed the diagnosis of granular cell tumor which is positive for S100 protein and CD68 antibodies." (PMID 29925410, 2018). "Strong staining of S-100 protein, CD68, vimentin, E-cadherin and low proliferative activity observed with Ki-67 expression confirmed the diagnosis of a granular cell tumor." (PMID 28057062, 2017). "CD68 is a marker of lysosomal activity and is found in both perineural Schwann cells and 90% of granular cell tumors." (PMID 26491597, 2015). "Based on our immunohistological findings, granular cell tumors may be derived from Schwann cells, and the presence of CD68 indicates that Wallerian degeneration after nerve injury may be a contributor to tumor formation." (PMID 29329562, 2018). "Additional markers to identify granular cell tumors include CD68 and neurospecific enolase." (PMID 26491597, 2015). "Granular cell tumors are characterized by a granular cytoplasm which can be observed in SCO, but, in opposition to the SCO, granular cell tumour shows a strong expression of CD68." (PMID 21320334, 2011). "CD68 and PAS staining were generally negative or variably positive in pituicytoma but positive in granular cell tumor." (PMID 31689841, 2019).